BDNF (brain derived neurotrophic factor)
Diseases named in the same sentence as BDNF in open-access papers (continued):
Sharing a sentence is not in itself a finding about the gene and the disease.
ischemia (continued). "Furthermore, studies have indicated that BDNF may regulate neurogenesis after a neurological event, such as subarachnoid hemorrhage (SAH) or ischemia." (PMID 34768919, 2021). "However, despite this considerable circumstantial evidence, previous studies have not yet explored the effect of HIF-1α on BDNF/TrkB/CREB pathway in improving synaptic plasticity following ischemia/reperfusion injury." (PMID 32670026, 2020). "Reactive astrocytes express various neurovascular trophic factors and chemokines such as SDF-1α, VEGF, glial cell derived neurotrophic factor (GDNF), and brain-derived neurotrophic factor (BDNF), which may positively contribute to neurogenesis, angiogenesis and neurite outgrowth following ischemia." (PMID 30524673, 2018). "Mechanistically, upregulation of neurotrophic and growth factors, such as brain-derived neurotrophic factor (BDNF) induced by long-term DR could be partially responsible for increased protection, as BDNF has been shown to reduce neuronal injury after ischemia." (PMID 24705386, 2014). "The two-way ANOVA test indicated that ischemia and PDD diets significantly changed MDA levels (df = 3, F = 3.807, p = 0.0193) in the hippocampus, while there were no interactive effects of ischemia and PDD diets on Nrf2 and BDNF expression in the hippocampus." (PMID 32759679, 2020). "No BDNF+ cells were double labeled with TNF-α+ or IL-β+ cells in the brain, whether at the ischemia damaged areas or the intact areas." (PMID 30405724, 2018).
type 2 diabetes (117 papers, 2010 to 2025). "One study in people with type 2 diabetes found that low vitamin D status was associated with elevated BDNF levels, and subsequent vitamin D supplementation lowered BDNF levels while improving glycemic control." (PMID 41142318, 2025). "Serum BDNF levels are markedly reduced in type 2 diabetic patients with nephropathy and correlate with deficiencies in vitamins D, B12, folate, and zinc, as well as elevated IL-6 and IL-12." (PMID 41142318, 2025). "Mendelian randomization (MR) analysis found that genetically predicted higherserum BDNF levels were causally associated with reduced risks of type 2 diabetes,hyperlipidemia and hypertension." (PMID 41523972, 2025). "The use of DPP-4 inhibitors in the treatment of patients with type 2 diabetes was associated with increased serum BDNF levels and improved cognitive functions." (PMID 38510866, 2024). "This study was done to determine the association of serum brain-derived neurotrophic factor (BDNF) levels with DR in type 2 diabetic patients in a tertiary care hospital in North India." (PMID 39712817, 2024). "When compared to metformin alone, the use of DPP-4 inhibitors in the treatment of patients with type 2 diabetes was associated with increased serum BDNF levels and improved cognitive functions." (PMID 38510866, 2024). "Altered BDNF levels have been associated with increased appetite, obesity, type 2 diabetes, schizophrenia, depression, and neurodegenerative diseases such as Alzheimer’s." (PMID 36936159, 2023). "In the analysis with eight SNPs, we included variants in both the GCKR gene and the BDNF gene known to be associated with type 2 diabetes and body mass index (BMI) and smoking behaviour, respectively." (PMID 35679582, 2023). "A decrease in serum brain-derived neurotrophic factor (BDNF), a neurotrophin family member, is associated with peripheral neuropathy in patients with type 2 diabetes." (PMID 36051389, 2022). "In humans, individuals with type 2 diabetes showed low circulating levels of BDNF, and low plasma BDNF was associated with the severity of insulin resistance." (PMID 36329115, 2022). "In recent clinical study data of healthy and type 2 diabetes patients, diagnostic values of BDNF and NGF showed high sensitivity and specificity with very good AUC values." (PMID 35626286, 2022). "The effects of BDNF single-nucleotide polymorphisms (SNPs) on the risk of cardiovascular disease, type 2 diabetes, and metabolic syndrome have been investigated extensively." (PMID 34580389, 2021). "Third, hypertension and type 2 diabetes are associated with decreased BDNF expression in the endothelium." (PMID 29409455, 2018). "Currently, data are limited that examine the implications of cardiometabolic risk factors on BDNF in individuals with type 2 diabetes." (PMID 22880108, 2012). "Notably, engaging in 150 min or more of exercise per week was associated with a significant increase in BDNF levels in elderly patients with type 2 diabetes." (PMID 40933306, 2025). "The reduction in brain BDNF after being treated with risperidone, along with BDNF gene polymorphisms, might be a part of the mechanism causing risperidone-induced type 2 diabetes in people with autism spectrum disorder." (PMID 38375208, 2023). "The BDNF rs4923461 A-allele showed a tendency towards a reduced risk of type 2 diabetes, however, the association was merely nominally, with an OR of 0.87 (0.78–0.96, p = 0.008) per allele when adjusting for BMI, however, when omitting adjustments for BMI the nominally tendency disappeared." (PMID 21912638, 2011). "Despite this, the results of a study suggest that variants of BDNF Val/Met and Met/Met reduce the risk of glucose intolerance and T2D, and that those middle-aged people who present the variant BDNF Val/Val are prone to develop Type 2 Diabetes even with low energy and protein consumption." (PMID 33269104, 2020).
type 2 diabetes (continued). "Subgroup analysis shows that chronic exercise has a more significant effect on BDNF levels in patients with type 2 diabetes than acute exercise." (PMID 40933306, 2025). "Numerous clinical studies have demonstrated reduced serum BDNF levels in individuals with Type 2 diabetes." (PMID 41280373, 2025). "Some studies have reported decreased plasma BDNF levels in obese patients with severe metabolic syndrome, while others have found elevated serum levels of BDNF in newly diagnosed women with type 2 diabetes." (PMID 40697550, 2025). "The experiment concludes that aerobic exercise enhances cognitive function in type 2 diabetic mice by modulating the MALAT1/miR-382-3p/BDNF signaling pathway, facilitating neuronal growth and suppressing death." (PMID 40161268, 2025). "Their study proved that ZnONP treatment leads to increased BDNF gene expression, counteracting the hippocampal neurotoxicity induced by type 2 diabetes in rats." (PMID 38190061, 2024). "In a study conducted on a total of 420 participants (208 patients with type 2 diabetes and 212 controls), in addition to the lower cognitive test scores, lower levels of BDNF (p<0.001) were reported in patients with type 2 diabetes when compared to controls." (PMID 38510866, 2024). "No other significant difference was observed in BMI, physical activity levels, socioeconomic status, type 2 diabetes, hypertension, systolic and diastolic blood pressure, smoking status, BDNF levels, and antidepressant medicine intake across tertiles of MDS." (PMID 37596403, 2023). "Previous studies have reported that decreased BDNF concentrations are found in type 2 diabetes patients." (PMID 38375208, 2023). "In a mouse model of type-2 diabetes, Sirt1 activation inhibited microglial activation by upregulating BDNF." (PMID 36725745, 2023). "Increased BDNF concentrations in persons with Type II Diabetes illicit increased metabolic effects such as the upregulations of neurotrophin receptor tyrosine kinase (TrkB) and cAMP-response element binding protein (CREB) pathways." (PMID 36138878, 2022). "According to our findings, genotype distribution of BDNF Val66Met (rs6265) in type 2 diabetes population was 54.9%, 35.2% and 9.9% for Val/Val, Val/Met and Met/Met." (PMID 34580389, 2021). "We performed a systematic review and meta-analysis to compare circulating BDNF levels in individuals with type 2 diabetes (T2D) or other glycemic disorders with healthy controls and to evaluate correlation between BDNF concentrations with glycemic profile." (PMID 34215825, 2021). "There are multiple studies linking circulating BDNF concentration to type 2 diabetes in humans and mice as well as in type 1 diabetic patients." (PMID 33178692, 2020). "BDNF concentration was much higher in patients with type 2 diabetes than in the healthy control group." (PMID 32012942, 2020). "Serum levels of BDNF in the diabetes type 2 group and the control group were higher compared to the diabetic peripheral neuropathy group." (PMID 32012942, 2020). "There is a significant decline in serum BDNF levels in type 2 diabetics with retinopathy in comparison with the healthy control group." (PMID 33457130, 2020). "In patients with type 2 diabetes, BDNF concentration in serum correlated positively with HOMA-IR (as in the previous study), as well as with triglyceride level and white blood cells (WBC) level." (PMID 32012942, 2020). "They proved that the serum of patients with type 2 diabetes contained much higher levels of BDNF than the serum of the control group." (PMID 32012942, 2020). "In patients with type 2 diabetes, the concentration of BDNF is lower than in healthy control groups." (PMID 32012942, 2020). "The expression level of BDNF is significantly decreased in the hippocampus of both type 1 and type 2 diabetes rats." (PMID 31165005, 2019).
type 2 diabetes (continued). "For example, BDNF, a growth factor responsible for neuronal growth and survival, is decreased in patients with type 2 diabetes mellitus (T2DM), indicative of insulin sensitivity." (PMID 24473138, 2014). "The current paper introduces a receiver-operating characteristic (ROC) generalization curve to identify cut-off for the BDNF values in type 2 diabetes patients." (PMID 25587547, 2014). "The present study is the first to our knowledge to evaluate the effects of exercise training on serum BDNF specifically in individuals with type 2 diabetes or to directly compare the effect of different exercise modalities in a large randomized trial." (PMID 22880108, 2012). "Future studies should investigate the relevance of BDNF with measures of cognitive function specifically in individuals with type-2 diabetes." (PMID 22880108, 2012). "Conversely, other studies have found the opposite relationship, noting elevated serum BDNF levels in individuals with type 2 diabetes." (PMID 22880108, 2012). "Plasma BDNF decreases with indicators of renal function, such as decreased glomerular filtration rate and increased urinary albumin excretion, as well as duration and severity of illness in type 2 diabetes (Rozanska, Uruska & Zozulinska-Ziolkiewicz, 2020)." (PMID 41142318, 2025). "In rats with type 2 diabetes, irisin was shown to regulate the expression of BDNF and glycometabolism and may serve as a promising novel target for the treatment of diabetic mild cognitive impairment." (PMID 35627690, 2022). "Moreover, higher BDNF concentrations were also found in untreated newly diagnosed diabetic patients, but as well as in previous diagnosed type 2 diabetic patients." (PMID 34992516, 2021). "In this sense, the available evidence in the literature indicates that obese and type 2 diabetes people may have a negative regulation of BDNF levels compared to people who exercise regularly." (PMID 32825341, 2020). "To conclude, there are different opinions about serum BDNF levels in patients with type 2 diabetes." (PMID 32012942, 2020). "Furthermore, our data suggested that progenitor-specific reduction in pro-BDNF expression would be a promising strategy to prevent and treat chronic disorders related to adipose tissue aging, such as type II diabetes." (PMID 32489703, 2020). "Previous studies have found reduced serum levels of BDNF in patients with type 2 diabetes." (PMID 31165005, 2019). "This may suggest that life-style modifications can improve hippocampal function in patients with type 2 diabetes and that BDNF may be an important mediator of these effects." (PMID 29255413, 2017). "Part of this data was published in AS thesis and as the abstract “Increased Hippocampal Activity after a Lifestyle Intervention in Type 2 Diabetes -Brain-Derived Neurotrophic Factor As a Potential Mediator” at the Endocrine Society's annual conference 2016, Boston, MA, USA." (PMID 29255413, 2017). "There are various potential mechanisms that link BDNF and development of type 2 diabetes." (PMID 25587547, 2014). "The BDNF supplementation could provide an effective treatment of visceral obesity, hyperleptinemia and leptin resistance in type 2 diabetes." (PMID 24106476, 2013). "The finding of low BDNF levels both in neurodegenerative diseases and in type 2 diabetes may explain the clustering of these diseases." (PMID 22474595, 2012). "BDNF has been studied in various populations; however, the clinical significance of BDNF levels remains unclear in individuals with type 2 diabetes." (PMID 22880108, 2012). "It has been proposed that BDNF may be elevated in individuals with type 2 diabetes as a compensatory mechanism to provide additional neuroprotection due to the presence of chronic hyperglycemia and other cardiometabolic risk factors." (PMID 22880108, 2012).
type 2 diabetes (continued). "BDNF rs4923461 displayed a borderline BMI-dependent protective effect on type 2 diabetes (0.87 (0.78–0.96, p = 0.008)), whereas SH2B1 rs7498665 associated with nominally BMI-independent increased risk of type 2 diabetes (1.16 (1.07–1.27, p = 7.8×10−4))." (PMID 21912638, 2011). "Additionally, serum levels of BDNF have also been shown to be decreased in patients with type 2 diabetes compared to healthy controls." (PMID 20404913, 2010). "In addition, Type 2 diabetes mellitus (T2DM) is known to be associated with an increased risk of dementia, and 12-week fasting in T2DM rats improves behavior and brain function by increasing the levels of NT3 and BDNF." (PMID 34899367, 2021). "While such individuals may arguably benefit most from interventions that elevate BDNF concentration, physiological responses to heat stress can be impacted by old age and health conditions such as type II diabetes mellitus; reinforcing the need for studies in specific populations." (PMID 34882699, 2021). "As most patients with type 2 diabetes are obese, they could have reduced BDNF levels." (PMID 34215825, 2021). "Therefore, to improve the glycemic control in type-2 diabetes more effectively, the simultaneous treatment with BDNF and the drug having a function to alleviate impaired insulin secretion might be required." (PMID 24106476, 2013). "However, the relationship of BDNF with cardiometabolic risk factors is unclear, and the effect of exercise training on BDNF has not been previously explored in individuals with type 2 diabetes." (PMID 22880108, 2012). "The present study aimed to evaluate the effect of DPP-4 inhibitors on sMMSE scores, serum BDNF, and PTX-3 levels in patients with type 2 diabetes, compared with patients who only use metformin treatment." (PMID 38510866, 2024). "The target genes that were significantly enriched for the development of type II diabetes mellitus in both modules are GNAS, PRKACB, PRKCE, MAP4K4, PEA15, and BDNF." (PMID 32993798, 2020). "From this information, it can be considered for the analysis if hsa-miR-933 can regulate the overexpressed PEA15, downregulated BDNF, or other ATF2 target genes (PRKACB, GNAS, PRKCE, and MAP4K4) to control type II diabetes mellitus." (PMID 32993798, 2020). "Alterations in plasma concentrations of BDNF and LXA4 in STZ-induced type 2 diabetes animals was estimated." (PMID 31823816, 2019). "Thus, our results suggest that BDNF may be an important factor mediating the positive effects of these interventions on functional brain responses within the hippocampus in patients with type 2 diabetes." (PMID 29255413, 2017). "The GMDR has been successful in identifying the significant interaction of CHRNA4 with CHRNB2, NTRK2 with BDNF, and GABBR1 with GABBR2 in nicotine dependence, of LEPR and ADRB2 in obesity, and of HNF4A and KCNJ11 in type 2 diabetes (T2D)." (PMID 23626757, 2013). "ARDs are characterized by accelerated atherosclerosis, increased incidence of cardiovascular diseases, type 2 diabetes, and other comorbidities, which are partly mediated by dysregulation of signaling pathways involving adropin, including NB-3/Notch, AKT/CREB/BDNF, and VEGFR2/PI3K/AKT." (PMID 41007860, 2025). "This study aimed to evaluate the association between DPP-4 inhibitor use and cognitive functions, serum brain-derived neurotrophic factor (BDNF), and pentraxin-3 (PTX-3) levels in patients with type 2 diabetes, compared with the patients who only use metformin treatment." (PMID 38510866, 2024). "Our approach delineated that hsa-miR-933 might control the hyperglycemic condition and hyperinsulinism by regulating ATF2 target genes MAP4K4, PRKCE, PEA15, BDNF, PRKACB, and GNAS which can otherwise lead to the development of type II diabetes mellitus." (PMID 32993798, 2020). "Some studies have found that BDNF levels are lower in individuals with type 2 diabetes compared to non-diabetic individuals both in plasma and serum." (PMID 29930382, 2018).
type 2 diabetes (continued). "Our study provides a comprehensive biochemical and immunological profile, simultaneously assessing BDNF, vitamins D, B12, folic acid, zinc, calcium, IL-6, and IL-12, in well-matched groups of type 2 diabetic patients with and without nephropathy, as well as healthy controls." (PMID 41142318, 2025). "BDNF may then be involved in pathophysiological processes of metabolic diseases such as insulin resistance and Type 2 Diabetes (T2D), however the exact mechanism has not yet been elucidated." (PMID 33269104, 2020). "Brain-derived neurotrophic factor (BDNF) is a neurotrophin, which plays an important role in the central nervous system, and systemic or peripheral inflammatory conditions, such as acute coronary syndrome and type 2 diabetes mellitus (T2DM)." (PMID 29062839, 2017).